MUC5AC (mucin 5AC, oligomeric mucus/gel-forming)
Diseases named in the same sentence as MUC5AC in open-access papers (continued):
Sharing a sentence is not in itself a finding about the gene and the disease.
inflammatory bowel disease (7 papers, 2013 to 2023). A spectrum of small and large bowel inflammatory diseases of unknown etiology. "Ectopic expression of MUC5AC was observed in the inflammatory bowel diseases and in UC-associated dysplasia/neoplasms." (PMID 32168759, 2020). "Some reports have demonstrated findings of ectopic gastric phenotypic expression, such as of MUC5AC, in inflammatory bowel diseases (IBDs) and in UC-associated dysplasia/neoplasms." (PMID 24829572, 2014). "Several reports also have demonstrated ectopic gastric phenotypic expression, such as of MUC5AC, in the inflammatory bowel diseases and in UC-associated dysplasia/neoplasms." (PMID 23691335, 2013). "MUC5AC is a gel-forming mucin that is thought to interact with another trefoil factor, TFF1, uniquely co-upregulated in the gut affected by inflammatory bowel disease, and likely has a role in clearance of pathogens as well as promotion of barrier repair." (PMID 37317221, 2023). "Gel-forming mucins (particularly MUC5AC and MUC6) may play a role in epithelial wound healing after mucosal injury in inflammatory bowel disease, in addition to providing mucosal protection." (PMID 24829572, 2014). "MUC5AC and TFF1 expression in goblet cells is common in inflammatory bowel disease and other inflammatory conditions of the colon, suggesting that these changes represent a nonspecific repair function of the colon cells to compensate for damage to barrier function." (PMID 24829572, 2014). "The gel-forming mucins (particularly MUC5AC and MUC6) may have a role in epithelial wound healing after mucosal injury in inflammatory bowel disease, in addition to providing mucosal protection." (PMID 23691335, 2013). "MUC5AC and TFF1 expression in goblet cells is common in inflammatory bowel disease and other inflammatory conditions of the colon, suggesting that these changes may represent a nonspecific repair function of the colon cells to compensate for damage to barrier function." (PMID 23691335, 2013).
pancreatic adenocarcinoma (7 papers, 2020 to 2023). "The results of our study demonstrate that MUC5AC expression is more frequent inductal pancreatic adenocarcinoma (71% of 423 cancers) than in carcinomas of theampulla Vateri (43% of 47 cancers)." (PMID 35764407, 2022). "High serum MUC5AC had 82% sensitivity and 100% specificity in diagnosing high-grade invasive lesions, which demonstrates its utility in the differential diagnosis of mucinous papillary tumours against probable pancreatic adenocarcinomas." (PMID 35454771, 2022). "MUC5AC has its highest expression in premalignant lesions and pancreatic adenocarcinomas." (PMID 35454771, 2022). "Additionally, mucin MUC5AC, a direct SHH target in pancreatic adenocarcinoma cells, is activated and its localization to intercellular junctions destabilizes E-cadherin adhesions." (PMID 37255594, 2023). "That MUC5AC expression was detectable in more than 70% of pancreatic adenocarcinomas,but completely absent in normal and inflamed pancreatic tissue, suggests a highdiagnostic utility of MUC5AC IHC." (PMID 35764407, 2022). "However, between 40–70% of patients with pancreatic adenocarcinoma do not have an elevated CEA; thus, probes targeting other biomarkers, such as MUC5AC, are necessary." (PMID 37241027, 2023).
Barrett esophagus (6 papers, 2008 to 2025). Esophageal lesion lined with columnar metaplastic epithelium which is flat or villiform. "Immunohistochemistry staining of Muc5AC (one of the mucins produced in Barrett's esophagus) reveals its expression in these cells." (PMID 18953412, 2008). "Additionally, a variety of mucins are expressed in Barrett's esophagus, notably MUC5AC, which is normally expressed in the gastric epithelium." (PMID 18953412, 2008).
chronic pancreatitis (6 papers, 2015 to 2024). A chronic inflammatory process causing damage and fibrosis of the pancreatic parenchyma. "Serum MUC5AC levels have been shown to be increased in patients with PDAC compared with both benign and chronic pancreatitis cohorts, with MUC5AC performing on par with CA19-9, though again, the combination of the two produced the best results." (PMID 36969742, 2022). "When used along with CA 19-9, serum MUC5AC is useful in that it helps differentiate PDA from other benign conditions like chronic pancreatitis." (PMID 34205412, 2021). "When MUC5AC is added to CA 19-9, specificity improves from 43% to 83% and sensitivity from 79% to 83% in differentiating cancers from chronic pancreatitis/normal." (PMID 34205412, 2021). "In a multicenter study, to differentiate PC from chronic pancreatitis and their benign controls, mucin (MUC5AC) alone or in combination with CA19-9 could be a potential diagnostic/prognostic biomarker." (PMID 30567565, 2018). "While MUC1, MUC4, and MUC5AC are the most differentially overexpressed mucins in human PDAC, the selective increase of MUC6 expression was identified as a potential biomarker for human chronic pancreatitis when compared to normal pancreas and PDAC in an unbiased screen." (PMID 25803032, 2015).
ductal adenocarcinomas (6 papers, 2010 to 2022). "The study indicated a stepwise upregulation of MUC5AC from high-grade pancreatic intraepithelial neoplasia to invasive ductal carcinomas." (PMID 32028958, 2020). "MUC5AC expression was a benefit to better survival of patients with pancreas invasive ductal carcinoma." (PMID 28938681, 2017). "MUC5AC expression in differentiating ductal adenocarcinomas from benign conditions demonstrated better operating characteristics than either MUC1 or MUC6." (PMID 23197977, 2012). "Both membrane-bound (MUC1, MUC3, MUC4) and secreted mucins (MUC2, MUC5AC, MUC5B, MUC6) are upregulated in ductal adenocarcinoma of the breast." (PMID 30682816, 2019). "It has been known that MUC5AC de novo expression occurred in the invasive ductal carcinoma and pancreatic intraepithelial neoplasm with no detectable expression in normal pancreas, however, its function remains uncertain." (PMID 20492722, 2010).
esophageal adenocarcinoma (6 papers, 2008 to 2025). A malignant tumor with glandular differentiation arising predominantly from Barrett mucosa in the lower third of the esophagus. "The expression of Muc5ac in esophageal adenocarcinoma may be more sensitive than that in ESCC." (PMID 36430789, 2022).
gastric ulcer (6 papers, 2019 to 2024). An ulcerated lesion in the mucosal surface of the stomach. "Studies on gastric ulcers have indicated that mucins, present in mucus, are among the main protective components of the gastric mucosa, including MUC5AC." (PMID 38666018, 2024). "According to the results of qRT-PCR, the high-dose FPH treatment significantly increased the mRNA expression of MUC5AC and MUC6 in the gastric tissues of mice with ethanol-induced gastric ulcers." (PMID 36552666, 2022).
mucinous carcinoma of the ovary (6 papers, 2015 to 2024). "Two biopsies from two different mucinous ovarian carcinomas were positive for both MUC5AC and MUC16." (PMID 26075384, 2015). "Moreover, ovarian mucinous adenocarcinomas are negative for β-catenin and positive for MUC5AC, whereas mCRC exhibits a reverse pattern." (PMID 28730323, 2017).
pneumonia (6 papers, 2022 to 2025). An acute, acute and chronic, or chronic inflammation focally or diffusely affecting the lung parenchyma, caused by an infection in one or both of the lungs (by bacteria, viruses, fungi, or mycoplasma.). "As a result, this reinforces that these pathways may be an identifiable component of the polygenic architecture of pneumonia that could be used to direct inhibitors of MUC5AC to patients with elevated pneumonia genetic risk amongst protein modification processes such as glycosylation." (PMID 35768473, 2022). "Therefore, we can predict the serum LDH level by detecting the expression level of MUC5AC in sputum, so as to predict the severity of pneumonia in children earlier." (PMID 40600698, 2025). "The abnormal expression of CYP1A1 and MUC5AC contributes to the progression of pneumonia." (PMID 38137330, 2023). "We also were able to replicate the overrepresentation of the pneumonia polygenic signal within protein modification pathways in which MUC5AC participates in the independent UKBB cohort, suggesting that a PES to direct mucin inhibitors may be particularly clinically tractable." (PMID 35768473, 2022). "High expression of MUC5AC in BALF is mostly in the airway of the children with RMPP, and the pneumonia progresses rapidly." (PMID 40600698, 2025). "In earlier research, we established and evaluated a severe pneumonia model in high-load MP-infected mice and showed that YQDP regulates the TLR2/MyD88/NF-κB signaling pathway, Aquaporin5 (AQP5), and Mucin 5ac (MUC5ac) to regulate SMPP." (PMID 38694915, 2024). "Whilst MUC5AC did not have a cis-heritable GReX model available for FOCUS, eQTL annotation of individual SNPs consistently suggested that upregulated mRNA expression of MUC5AC was associated with elevated odds of pneumonia." (PMID 35768473, 2022).
pulmonary mucoepidermoid carcinoma (6 papers, 2016 to 2021). A lung carcinoma characterized by the presence of malignant non-keratinizing squamoid cells, mucin-producing cells and intermediate type cells. "Additionally, different IAV strains (seasonal and pandemic) and different subtypes (H1N1 and H3N2) induced different levels of MUC5AC expression in an NCI-H292 human pulmonary mucoepidermoid carcinoma cell line." (PMID 32599823, 2020). "In our previous study, ATP was shown to induce MUC5AC gene expression via the P2Y2 receptor and the MAPK pathway in NCI-H292 (mucoepidermoid pulmonary carcinoma) cells." (PMID 27034593, 2016).
squamous carcinoma (6 papers, 2016 to 2025). "Concretely, Epi2_MUC5B represented adenocarcinoma cell (MUC5B, MUC16, MUC5AC), while Epi4_MYC harbored conventional squamous cell carcinoma features, such as high expression of KRT6A and MYC." (PMID 40657372, 2025). "The aim of this study was to examine the combination of cytokeratin 5/6, p63, p40, and MUC5AC for distinguishing squamous cell carcinoma (SCC) from the adenocarcinoma in the cervix (AEC)." (PMID 32843061, 2020). "In the following study, we examined the combination of cytokeratin 5/6, p63, p40 and MUC5AC for distinguishing squamous cell carcinoma (SCC) from adenocarcinoma of the cervix (AEC)." (PMID 32843061, 2020). "MUC5AC may be useful as a biomarker for differential diagnoses between squamous carcinoma and adenocarcinoma of the cervix." (PMID 32843061, 2020). "However, studies have shown that focal positivity of MUC5AC may also occur in a few squamous cell carcinomas." (PMID 41333217, 2025). "Thus, we speculated that MUC5AC could be expressed in other adenocarcinomas and might be used for the differential diagnosis of adenocarcinoma and squamous carcinoma." (PMID 32843061, 2020).
bronchitis (5 papers, 2013 to 2024). An acute or chronic inflammatory process affecting the bronchi. "Significance remained for bronchitis, wheeze and hay fever, suggesting that associations with MUC5AC rs 1132440 are stronger than those with MUC5AC TR." (PMID 23551418, 2013). "The association of MUC5AC with bronchitis is only significant in individuals who lack the IL1RN*2 (risk) allele and only in individuals homozygous for the ERBB1 common rs2227983(R) allele—that is non-carriers of the rarer K allele." (PMID 23551418, 2013). "Both asthmatic and bronchitis respiratory secretions contained more MUC5AC mucin compared to those collected from normal individuals." (PMID 38339210, 2024). "In their paper, the effects of PG on oversecretion of pulmonary mucin (MUC5AC) in SO2-induced bronchitis in rats were examined." (PMID 33138217, 2020). "A novel association between bronchitis and an ERBB1/EGFR SNP rs2227983 was also identified and possible gene–gene interactions between MUC5AC and ERBB1 and IL1RN are described." (PMID 23551418, 2013). "Significant interactions with respect to bronchitis were identified between MUC5AC rs1132440 and ERBB1 rs2227983 (P = 0.019), IL1RN VNTR (P = 0.009) and TNFA rs1800629 (P = 0.046)." (PMID 23551418, 2013). "A novel association between bronchitis and a non-synonymous functional ERBB1 SNP, rs2227983 (aka epidermal growth factor receptor:R497K, R521K) is also reported and evidence presented of interaction between MUC5AC and ERBB1 and between MUC5AC and IL1RN with respect to bronchitis." (PMID 23551418, 2013).
colonic adenocarcinoma (5 papers, 2004 to 2023). "Indeed, a recent study revealed the role of MUC5AC, MUC1 and proteoglycans in the inhibition of E-cadherin function associated with invasiveness of HT-29 colon adenocarcinoma cell variants." (PMID 14760390, 2004). "The human colonic adenocarcinoma cells HT29-18N2 (N2) differentiate to goblet cells upon starvation in protein-free medium, which increases the production of MUC5AC." (PMID 23741618, 2013). "We could also detect the gastric mucins MUC5AC and MUC1 in these cell lines, which is explained by that they are established from human colon adenocarcinomas, and cancer is known to induce changes in type of mucin production." (PMID 23869232, 2013). "MUC5AC is highly expressed in normal prostatic glandular tissue and in colon adenocarcinomas, while MUC4, MUC5B and MUC6 are not expressed in prostatic glandular tissue." (PMID 14760390, 2004). "Ninety per cent of metastatic colonic adenocarcinomas expressed MUC2, but none expressed MUC5AC." (PMID 31689847, 2019).
dysplasia (5 papers, 2014 to 2023). A usually neoplastic transformation of the cell, associated with altered architectural tissue patterns. "The present study demonstrates the ability of fluorescent anti-MUC5AC antibodies to specifically target and label colonic polyps containing high-grade dysplasia and intramucosal adenocarcinoma in CPC-APC mice." (PMID 37185743, 2023). "Specifically, during normal esophageal squamous, BE metaplasia, dysplasia, and EAC progression there is a progressive increase in TFF2, TFF3, MUC2, MUC5AC, MUC6, CDX2 with the development of intestinal metaplasia." (PMID 36994101, 2023). "We performed immunostaining for β-catenin, MLH1, and mucins (e.g., MUC2, MUC5AC, MUC6, and CD10); targeted next-generation sequencing; and microsatellite instability (MSI) testing in 8 SSA/P lesions comprised of 4 SSA/Ps with high-grade dysplasia and 4 SSA/Ps with submucosal carcinoma." (PMID 30458818, 2018).
mucinous tumors (5 papers, 2015 to 2023). "Papillary structures in cancer tissues of main ducts, interlobular or intralobular ducts and mucinous neoplasms were MUC5AC positive, while tubular and/or poorly differentiated structures were MUC5AC negative." (PMID 34205412, 2021). "Our data on MUC2 and MUC5AC expression in mucinous tumors were similar to the literature with low expression for MUC2 (2/13) and high expression (11/13) for MUC5AC." (PMID 36367122, 2023).
ovarian carcinoma (5 papers, 2009 to 2024). A malignant neoplasm originating from the surface ovarian epithelium. "In addition to PDAC, esophageal, gastric, colon, and ovarian cancer have high expression of MUC5AC, and several of these cancers also have a high rate of metastasis to the liver." (PMID 37241027, 2023). "The relative abundance of MUC2 compared to MUC5AC may be used for differential diagnosis with mucinous implants of ovarian cancer (OC), in which MUC5AC is, in most cases, the predominant mucin." (PMID 33266161, 2020). "In particular, a combined panel of MUC4, MUC5AC, and MUC16 may offer an effective and reliable diagnostic system and target for the management of various histological grades and types of ovarian cancer, although their biological functions are not clearly defined." (PMID 20034397, 2009).
tubular adenocarcinoma (5 papers, 2018 to 2025). An infiltrating adenocarcinoma in which the malignant cells form tubular structures. "The immunostaining results showed that the foveolar-type papillary adenocarcinoma was positive for MUC5AC and had a high index of Ki-67, but the pyloric gland-type tubular adenocarcinoma was positive for MUC6 and had a low index of Ki-67." (PMID 38725617, 2024). "The glandular component was a tubular adenocarcinoma, showing a MUC5AC-positive gastric type." (PMID 35596001, 2022).
allergic rhinitis (4 papers, 2016 to 2025). Inflammation of the nasal mucous membranes caused by an IgE-mediated response to external allergens. "In addition, miR-15a-5p has been proven to be involved in allergic rhinitis immune response by inhibiting IL-13-induced expression of GM-CSF, eotaxin and MUC5AC nasal epithelial cells." (PMID 40076712, 2025).
colorectal adenoma (4 papers, 2008 to 2020). An adenoma that arises from the colon or rectum. "The MUC5AC gene product, which is normally secreted in the stomach, but is absent from normal colon, is frequently found in colorectal adenomas and in the area surrounding the adenoma." (PMID 21152122, 2010).
colorectal polyps (4 papers, 2006 to 2020). "MUC5AC is a secreted mucin aberrantly expressed by colorectal polyps and carcinoma." (PMID 16409634, 2006). "For instance, there is a large body of controversy regarding the alterations of MUC5AC and MUC6 in colorectal polyps." (PMID 20929551, 2010). "The aim of the present study was to determine the pattern of expression of MUC1, MUC2, MUC5AC and MUC6 in colorectal polyps and to evaluate the applicability of using mucin expression in predicting the extent of malignant transformation in colorectal polyps." (PMID 20929551, 2010). "MUC1, MUC2, MUC5AC, and MUC6 have the potential to be used as predictors of malignant transformation and invasion to mucosa or the muscularis mucosae in colorectal polyps." (PMID 20929551, 2010). "In general, majority of colorectal polyps in this study had negative expression of MUC5AC." (PMID 20929551, 2010).
colorectal tumors (4 papers, 2009 to 2022). "(E) Consensus molecular subtype (CMS) distribution of high and low MUC5AC-expressing colorectal tumours (Jorissen cohort)." (PMID 35131032, 2022). "Perhaps consistent with the requirement for Sox2 in goblet cell differentiation, Sox2 activated a Muc5AC-luciferase reporter in colorectal tumors, and Muc5B mRNA was increased in lung when Sox2 was overexpressed in a transgenic mouse model." (PMID 20011520, 2009). "However, in some cases, decreased expression of secreted mucins (i.e. MUC2 and MUC5AC) is an indicator of more aggressive colorectal tumour, possibly because these cells are more dedifferentiated and thus more invasive." (PMID 35131032, 2022). "This association was independent of the tumor localization, as the frequency of dMMR cancers is higher in proximal and distal colorectal tumors with MUC5AC positive in comparison with MUC5AC-negative cancers." (PMID 33373033, 2021). "Clinical studies have shown that the absence of MUC5AC expression could serve as an indicator of a more aggressive colorectal tumor and that patients with MUC5AC-negative expression had lower survival rates." (PMID 30922401, 2019).
Crohn disease (4 papers, 2015 to 2024). A gastrointestinal disorder characterized by chronic inflammation involving all layers of the intestinal wall, noncaseating granulomas affecting the intestinal wall and regional lymph nodes, and transmural fibrosis. "MUC5AC mRNA expression can be upregulated in some diseases in which stress is a contributing factor to inflammatory pathologies such as Crohn’s disease, which affects the proximal small intestine, although most commonly the ileum and colon." (PMID 39044931, 2024). "In Crohn ́s disease, MUC5AC expression is known to be induced in the intestine together with MUC5B and MUC6." (PMID 26162072, 2015).